IL1B (interleukin 1 beta)
Diseases named in the same sentence as IL1B in open-access papers (continued):
Sharing a sentence is not in itself a finding about the gene and the disease.
myocarditis (continued). "Of clinical relevance, treatment with IL-1β neutralizing antibody increased survival and decreased the myocarditis score in CVB3-induced mouse model of myocarditis." (PMID 40146392, 2025). "In CVB3 infection, the expression of interferon beta (IFN-β, gene IFNB1), tumor necrosis factor alpha (TNF-α, gene TNF), interleukin-1 beta (IL-1β, gene IL1B) and interleukin-8 (IL-8, gene CXCL8) are highly upregulated and correlate with myocarditis severity." (PMID 41156753, 2025). "Two well-described cytokines involved in the progression of myocarditis, TNF-ɑ and IL-1β, have been demonstrated to impair cardiomyocyte ion currents, compromise contractile function, and disrupt Ca2+ homeostasis." (PMID 40146392, 2025). "The intersection of LC and myocarditis-related targets was visualized with a Venn diagram, revealing 51 common targets, including TNF, IL1B, IL6, and others." (PMID 41585875, 2025). "In light of these events, early reduction of IL-1β and IL-6 is imperative for managing post-vaccine cytokine storms, ACS, and myocarditis." (PMID 39452475, 2024). "We found previously that IL-1β levels are increased in the heart of males with myocarditis, while cardiac levels of TNFα are increased in females in our CVB3 model of myocarditis." (PMID 39696682, 2024). "Most cardiac inflammatory cells during acute myocarditis at day 10 pi are CD11b+ (macrophages and mast cells) that express TLR4 and release IL-1β." (PMID 39696682, 2024). "It has been reported that the proinflammatory cytokines IL-1β, IL-6, and TNF-α are increased in acute myocarditis." (PMID 35265721, 2022). "Cardiac IL-18 and IL-1β levels, the outcome of NLRP3 inflammasome activation, in male mice with myocarditis were significantly higher compared with females." (PMID 35251049, 2022). "Increased production of IL-1β and TNF-α in response to CVB3 virus infection induced myocarditis in a mouse model." (PMID 32269577, 2020). "Testosterone increases mast cell and macrophage numbers in the heart of males with myocarditis and upregulates cardiac TLR4, IL-1β, and IL-18." (PMID 29669571, 2018). "Further detection of inflammatory factors, including Tnf-α, Il-1β, Il-6, and Mcp-1, also supports the notion that geniposide attenuates HFD-induced myocardial inflammation." (PMID 30533173, 2018). "Infection with CBV3, an enterovirus of the Piconaviridae family, induced production of IL-1β in cardiac tissues of VMC mice, which was positively correlated with the severity of myocarditis." (PMID 28832767, 2017). "On day 7, the cardiac IL-1β, TNF-α, IL-6 and IL-17A levels were significantly downregulated in the group of 0.2 and 0.4 mg/kg nicotine compared to the myocarditis group." (PMID 26507386, 2015). "Furthermore, IL-1β and IL-18 levels are elevated in myocarditis, implicating inflammasome activation; indeed, myocardial biopsies from myocarditis patients have shown increased NLRP3 and IL-1β expression." (PMID 40832143, 2025). "Particularly, male mice with CVB3-induced myocarditis display a higher Th1 response and release of pro-inflammatory cytokines such as IL-1β, IL-18, and IFN-γ, whereas female mice develop predominantly an anti-inflammatory Th2 response in the context of CVB3-induced myocarditis." (PMID 39273613, 2024). "However, the inflammatory M1 polarity genes (IL-1β, IL-6, TNF-α and MCP-1) were significantly increased, with increased rates of myocarditis in the heart of KO mice compared to those of WT mice." (PMID 36982385, 2023). "Moreover, the cytokine levels of TNF-α, IL-1β, and IL-18 were significantly reduced in LQF group, suggesting that LQF can alleviate myocardial inflammation induced by MI, thereby improving the cardiac function." (PMID 35310035, 2022). "The repair role of APE1/Ref-a is also suggested from findings of a murine myocarditis model in that APE1/Ref-1 is elevated at a later time point, in contrast to that of other markers, such as IL-1β, IFN-β, and IL-6 expression, which disappear with a decline in virus titer." (PMID 35052869, 2022).
myocarditis (continued). "On the other hand, the high virulent T. cruzi strains induce the upregulation of NLRP3, caspase-1, IL-1β, TNF-α, and iNOS mRNA in heart muscle, compared to low and medium virulent strains, which may contribute to myocarditis and death." (PMID 34336720, 2021). "Myocarditis-NCV was classified as immune-mediated when anti-heart Abs were positive, viruses in cardiac tissue were absent, myocardial TLR-4 was overexpressed and inflammatory cytokines (IL-1β, IL-6, IL-8, TNF-α) in serum samples were elevated." (PMID 33355356, 2021). "In this study we found that exposure to BPA in drinking water elevated proinflammatory cytokines/ receptors in the heart of female mice during CVB3 myocarditis that would typically be elevated in male mice or men with mycarditis such as TLR4, caspase-1, IL-1β, IL-17A, and IFNγ." (PMID 31551929, 2019). "TLR4 and IL-12Rβ1 might share common downstream pathways that directly affected IL-1β and IL-18 production, and IL-1beta and IL-18 played an important part in the pathogenesis of CVB3-induced myocarditis." (PMID 29854842, 2018). "MSCs increased significantly the myocardial expression of HGF and decreased the expression of the proinflammatory cytokines TNFα, IL1β and IL6 as well as the severity of myocarditis and ameliorated the left ventricular dysfunction measured by conductance catheter." (PMID 22815907, 2012). "In addition, it’s found for the first time that P2X7/NLRP3/IL-1β, PIP2, and MAPK signaling pathways are involved in the regulatory effect of PE on myocarditis, providing a prospect for development and application of myocarditis drugs." (PMID 40642003, 2025). "The results show that the most common cytokines to be elevated in the peripheral blood during ICI myocarditis are IL-6 and TNF-α with a surprising minority of patients with IFN-γ elevation and none with IL-1β elevation." (PMID 38785743, 2024). "Of particular note, only blockade of IL-1β, but not blockade of TNF-α, reduced the myocarditis in the LCWE-injected mice." (PMID 28400731, 2017). "We found that deguelin could efficiently decrease the expression of Akt1 and p-Akt but not Akt, Besides, deguelin increased the IL-1β, TNF-α expressions, aggravated the inflammation and fibrosis, therefore, deteriorated myocarditis." (PMID 32128091, 2019). "In addition, EMBs from patients without myocarditis or viral DNA tended to display lower mRNA expression levels of nucleotide-binding oligomerization domain-containing protein 2, adaptor protein ASC, and interleukin-1 beta compared to the other groups (N = 4–6 patients per group)." (PMID 35215893, 2022).
chronic periodontitis (97 papers, 2012 to 2026). A chronic inflammatory process that affects the tissues that surround and support the teeth. "A very recent study involving Bayesian methods to rate meta-analysis data on polymorphisms in IL-1 genes identified the IL-1A/rs1800587 and IL-1B/rs1143634 polymorphism as noteworthy biomarkers for chronic periodontitis susceptibility." (PMID 36429405, 2022).
chronic obstructive pulmonary disease (96 papers, 2010 to 2026). A chronic and progressive lung disorder characterized by the loss of elasticity of the bronchial tree and the air sacs, destruction of the air sacs wall, thickening of the bronchial wall, and mucous accumulation in the bronchial tree. "Dysbiosis can lead to chronic inflammation, with elevated levels of pro-inflammatory cytokines, such as IL-6, TNF-α, and IL-1β, being linked to an increased risk of cardiac arrhythmias." (PMID 38892965, 2024). "Our global and targeted immunological biomarker analyses revealed the inflammasome‐associated cytokine IL‐1β, found in acute and chronic otitis media and chronic obstructive pulmonary disease, as one of the highest secreted inflammatory mediators." (PMID 36762431, 2023). "Our group has recently reported that elevated circulating levels of TNFα and IL-1b are responsible for higher susceptibility to cardiac arrhythmia in type 2 diabetic rats." (PMID 34623540, 2023). "Elevated circulating levels of TNFα and IL-1b mediate the higher susceptibility to cardiac arrhythmia in type 2 diabetic rats." (PMID 34623540, 2023). "IL-1β is a biomarker of inflammasome activation and is implicated in the pathogenesis of chronic obstructive pulmonary disease (COPD), a frequent comorbidity in PWH who smoke cigarettes." (PMID 40862746, 2025). "Owing to their pivotal roles in inflammation, IL-1β and IL-6 have been proposed as biomarkers of lung injury and airway inflammation, particularly in diseases such as chronic obstructive pulmonary disease (COPD), ALI and ARDS." (PMID 39949769, 2025). "During inflammatory processes, the effects of IL-1β include delay in action potential repolarization due to Ito reduction, that increases Ca+2 sparks, and the incidence of cardiac arrhythmias." (PMID 40356773, 2025). "The decrease in IL-1β levels after ExT, represents an additional potential effect to ameliorate cardiac arrhythmias." (PMID 40356773, 2025). "IL-1β is related to the characteristic pathological changes of the airway in patients with chronic obstructive pulmonary disease, chronic pulmonary inflammation and lung tissue damage." (PMID 36707853, 2023). "Several researches had shown that miR-155HG regulated the expression of TNF-α, IL-1β, IL-10, and IL-12, together with GM-CSF-mediated polarization of M1/M2 macrophages in the progression of chronic obstructive pulmonary disease (COPD)." (PMID 35434143, 2022). "In renal ischemia/reperfusion, IL-1β produced after sensing kidney injury prolongs QJ and sensitizes to cardiac arrhythmias." (PMID 36341442, 2022). "In vivo analysis of lung lavage confirmed elevated ATP, PGE2, and IL-1β concentrations compared with other lung-related diseases such as chronic obstructive pulmonary disease (COPD), indicating a strong and acute physical response to SARS-CoV-2." (PMID 34841222, 2021). "Additionally, the release of CXCL8 was observed together with IL-1β in cigarette smoker-associated chronic obstructive pulmonary disease (COPD) patients." (PMID 33613529, 2020). "Previous studies suggest that the downstream products of NLRP3 inflammasomes such as IL-1β or IL-18 are associated with the pathophysiology of smoke-driven chronic obstructive pulmonary disease (COPD) although direct evidence to link NLRP3 protein with the disease is sparse." (PMID 28056996, 2017). "P2X7R and Panx1 are shown to participate in neutrophil activity and recruitment, as well as IL-1β release in a study focusing on chronic obstructive pulmonary disease (COPD)." (PMID 27445679, 2016). "We show that IL-1β produced by DM heart macrophages targets cardiomyocytes to induce cardiac arrhythmias." (PMID 27882934, 2016). "Chronic obstructive pulmonary disease (COPD) is characterized by reduced lung function associated with increased local and systemic inflammatory markers, such as TNFα and IL-1β." (PMID 27883019, 2016).
chronic obstructive pulmonary disease (continued). "Genetic variants in the promoter region of the IL1B gene have been associated with negative outcomes in inflammatory conditions, such as rs4848306 in reactive septic arthritis and rs16944 in chronic obstructive pulmonary disease (COPD)." (PMID 40506975, 2025). "SCFAs (acetate, propionate, and butyrate) can enhance the expression of GPR43 while downregulating the expression of NLRP3, IL-18, and IL-1β, thereby strengthening the mucosal immune function of the gut and lungs in rats with chronic obstructive pulmonary disease." (PMID 40906358, 2025). "Moreover, several proinflammatory cytokines, such as TNF-α, IL-1β, and IL-17, have been shown to induce cardiac arrhythmias in various animal models." (PMID 37845390, 2023). "Previous studies demonstrated that Haemophilus influenzae leads to airway inflammation deterioration, induced by cigarette smoke exposure in COPD (chronic obstructive pulmonary disease) mice, and the production of the pro-inflammatory mediators interleukin-6 (IL-6) and IL-1β." (PMID 35158583, 2022). "Moreover, it has been recently demonstrated the role of both TNFα and IL-1b in the initiation and maintenance of cardiac arrhythmias in humans." (PMID 34202017, 2021). "Therefore IL-1β is pursued as a clinical target (for example, Canakinumab, which is used for treating autoinflammatory syndromes and in clinical trial for chronic obstructive pulmonary disease)." (PMID 27538513, 2016). "Similarly, studies from animal models have demonstrated that IL-1 cytokines such as IL-1α and IL-1β play critical roles in the pathogenesis of asthma, chronic obstructive pulmonary disease, acute lung injury and pulmonary fibrosis." (PMID 23029241, 2012). "In chronic lung disease models such as chronic obstructive pulmonary disease (COPD), in vitro and ex vivo studies revealed that MTAs reduced macrophage mitochondrial ROS, improved mitophagy, and attenuated IL-1β secretion." (PMID 41614806, 2025). "Here, we tested whether IL-1β contributes to systolic dysfunction and cardiac arrhythmias in CCC." (PMID 36341442, 2022). "TRPV4, a calcium permeable cation selective channel, was found to be involved in chronic obstructive pulmonary disease (COPD) through releasing ATP and IL-1β." (PMID 35002766, 2021). "Chronic obstructive pulmonary disease (COPD) is a chronic disease characterized by a progressive decline in lung function due to airflow limitation, mainly related to IL-1β-induced inflammation." (PMID 31601004, 2019). "IL-1β is also about 2–3-fold upregulated in small airway epithelial cells of chronic obstructive pulmonary disease (COPD) patients and seems to influence COPD airway inflammation." (PMID 30042333, 2018). "Foamy macrophages contribute significantly to the chronic inflammatory milieu of chronic obstructive pulmonary disease (COPD) by releasing pro-inflammatory cytokines such as IL-6, TNF-α, IL-1α, and IL-1β." (PMID 41009372, 2025). "Measuring 30 cytokines in 936 sputum samples from patients with chronic obstructive pulmonary disease, we observed significant increases (IL-17A, TNF-α, IL-1β, IL-10) between stable and exacerbation states." (PMID 38836471, 2024). "Patients with chronic obstructive pulmonary disease (COPD) have been found to have decreased SOCS5 levels, which underpins heightened levels of IL-1β and TNFα." (PMID 39676878, 2024). "In chronic obstructive pulmonary disease (COPD), activation of ERK produces pro-inflammatory cytokines, such as TNF-α, IL-1β, IL-6 and IL-8." (PMID 35889800, 2022). "In a mouse model of chronic obstructive pulmonary disease (COPD), dexamethasone not only downregulated NLRP3, caspase-1, and IL-1β but also upregulated the levels of SOD." (PMID 34512868, 2021).
chronic obstructive pulmonary disease (continued). "Soluble uric acid exerts an inflammation‐stimulatory effect and induced the production of tumor necrosis factor α (TNFα), interleukin (IL)‐6, and IL‐1β,25 it also involved in the lung injury, COPD (chronic obstructive pulmonary disease), and EP (eosinophilic pneumonia)." (PMID 34655117, 2021). "However, it is also important to consider the role of IL-1β as an anti-inflammatory target for chronic obstructive pulmonary disease (COPD; Dhimolea, 2010)." (PMID 33935886, 2021). "In rats with chronic obstructive pulmonary disease (COPD), TNF-α and IL-1β levels in the bronchoalveolar lavage fluid decreased after electroacupuncture." (PMID 28069040, 2017). "The proinflammatory cytokines interleukin (IL)-1α and IL-1β were significantly elevated in the lung-tissue and sputum samples of patients with chronic obstructive pulmonary disease who smoked compared to those of nonsmokers." (PMID 39335573, 2024). "Similarly, PDE4i roflumilast, FDA-approved therapy for severe chronic obstructive pulmonary disease (COPD), reduces IL-1β levels and obtains better clearance than ATT alone in the chronic TB mouse model after 8 weeks posttreatment." (PMID 37196131, 2024). "PTX3 expression is rapidly induced by proinflammatory cytokines, such as TNF-α and IL-1β, and PTX3 has thus been suggested to be a biomarker in inflammation-related diseases such as chronic obstructive pulmonary disease (COPD), hepatocellular carcinoma and liver fibrosis." (PMID 38243273, 2024). "In addition, RELMβ also promotes the expression of the inflammatory factors IL-8 and IL-1β by inducing phosphorylation of p38 MAPK in BECs, which is involved in airway inflammation in chronic obstructive pulmonary disease (COPD)." (PMID 36691020, 2023). "Our results here show that IL-1R blockade does not improve systolic function or reverse cardiac arrhythmias, indicating IL-1β/IL-1R signaling is not involved in its maintenance, as it is in other diseases." (PMID 36341442, 2022). "Our results indicate that IL-1β is not critical to the generation/maintenance of cardiac arrhythmias or systolic dysfunction found in CCC." (PMID 36341442, 2022). "IL-1β is a potent pro-inflammatory mediator, produced after the most frequent activation of the nucleotide-binding oligomerization domain-like receptor (NLR) containing purine domain-3 proven in chronic obstructive pulmonary disease and IPF." (PMID 35326173, 2022). "A previous study have reported that the expression and secretion of MMP-12 can be regulated by IL-1β and TNF-α in human airway smooth muscle cells, and thereby participated in diseases of the airway, such as chronic asthma or chronic obstructive pulmonary diseases (COPD)." (PMID 33935718, 2021). "In viral infections and patients with chronic obstructive pulmonary disease (COPD), ILC2s have been documented to convert to an ILC1-like phenotype characterised by T-bet expression and IFNg production in response to the cytokines IL-1b, IL-12 and IL-18." (PMID 38745765, 2024). "Therefore, there is a strong case for IL-1β being involved in the genesis and maintenance of heart insufficiency and cardiac arrhythmias, but we found here that it is not the case for CCC." (PMID 36341442, 2022). "In conclusion, the absence of functional IL-1β/IL-1R signaling did not prevent or reverse the decrease of SV or the incidence of cardiac arrhythmias induced by chronic T. cruzi infection, implying this is not a critical mechanism in generating or maintaining CCC." (PMID 36341442, 2022). "Interleukin (IL)-1α, IL-1β, IL-6, IL-8 and tumor necrosis factor (TNF)α contribute to inflammation in chronic obstructive pulmonary disease (COPD)." (PMID 33266187, 2020). "IL-1β is also elevated in lungs of patients with MUC5B hypersecretion respiratory disease, such as chronic obstructive pulmonary disease (COPD) and cystic fibrosis." (PMID 31309122, 2019).
chronic obstructive pulmonary disease (continued). "Common comorbidities, including obesity, diabetes, hypertension, chronic obstructive pulmonary disease (COPD), and chronic kidney disease (CKD), have been postulated to drive the systemic inflammatory state, as shown by elevated levels of circulating cytokines, including IL-1β, IL-6, CRP, and TNFα." (PMID 36818566, 2023).